KRTAP21-1 (keratin associated protein 21-1)
Description:
In the hair cortex, hair keratin intermediate filaments are embedded in an interfilamentous matrix, consisting of hair keratin-associated proteins (KRTAP), which are essential for the formation of a rigid and resistant hair shaft through their extensive disulfide bond cross-linking with abundant cysteine residues of hair keratins. The matrix proteins include the high-sulfur and high-glycine-tyrosine keratins.
Synonyms: KAP21.1
Tractability: No criterion of Open Targets' tractability assessment is met for any kind of drug.
Gene: Protein-coding gene on chromosome 21 (30,755,015 to 30,755,428, reverse strand). Ensembl gene ENSG00000187005.
Pathways (Reactome):
Developmental Biology: Keratinization
Gene Ontology:
Cellular component: cytosol
Genetic constraint (gnomAD): Loss-of-function variants: 0 observed, 2.22 expected, observed/expected ratio (o/e) 0, 90% interval 0 to 1.26. That is too few expected variants to judge how well the gene tolerates losing a copy. Missense variants: 75 observed, 98.66 expected, observed/expected ratio (o/e) 0.76, 90% interval 0.63 to 0.92. Synonymous variants: 29 observed, 39.91 expected, observed/expected ratio (o/e) 0.73, 90% interval 0.54 to 0.99.
Homologues: Orthologues: chimpanzee KRTAP21-1 (95% identical), dog KRTAP21-1 (78% identical).